TRPV3 (transient receptor potential cation channel subfamily V member 3)
Diseases named in the same sentence as TRPV3 in open-access papers (continued):
Sharing a sentence is not in itself a finding about the gene and the disease.
dermatitis (continued). "Through FDA-approved drug screening, researchers identified the antispasmodic flopropione as a selective TRPV3 inhibitor capable of alleviating skin inflammation." (PMID 40699677, 2025). "In the TRPV3 agonist carvacrol-treated mouse dermatitis and ear-swelling model, fluoxetine effectively reduced skin inflammation, epidermal thickening and ear swelling." (PMID 40699677, 2025). "In the course of animal experiments, fluoxetine mitigates carvacrol-induced TRPV3-related skin inflammation." (PMID 40699677, 2025). "Further in vivo evaluation shows that CA significantly reverses TRPV3-mediated skin inflammation induced by skin sensitizer carvacrol." (PMID 39202808, 2024). "We have also demonstrated that Scu alleviates 2,4-dinitrofluorobenzene (DNFB) and carvacrol-induced pruritus and dermatitis by specifically inhibiting transient receptor potential vanilloid 3 (TRPV3) channels." (PMID 39502535, 2024). "Suppression of TRPV3 channel function by gene knockout and pharmacological inhibitors has been shown to alleviate dermatitis and pruritus." (PMID 39202808, 2024). "In conclusion, we demonstrate that the antispasmodic agent flopropione inhibits TRPV3 channels and alleviates skin inflammation and injury." (PMID 38154600, 2023). "Concerning the therapy of dermatitis and pruritus, TRPV3 inhibitors, indeed, possess a significant potential." (PMID 37239947, 2023). "Flopropione not only provides a molecular tool but also holds repurposing potential for the prevention or therapy of TRPV3-related skin diseases such as dermatitis and chronic pruritus." (PMID 38154600, 2023). "Here, we report the identification of an antispasmodic agent flopropione that alleviates skin inflammation by selective inhibition of TRPV3." (PMID 38154600, 2023). "Activation of TRPV3 in keratinocytes leads to the release of interleukins and other inflammatory factors, contributing to skin inflammation and itch." (PMID 37629111, 2023). "Interestingly, several pro-inflammatory agents (bradykinin, PGE2, histamine, ATP) could increase the sensitivity of TRPV3 to warm temperatures, leading to an autocatalytic TRPV3-mediated increase in skin inflammation and associated symptoms, such as thermal hyperalgesia." (PMID 37239947, 2023). "The level of TRPV3 mRNA and/or protein in skin cells was reported to be altered in several conditions, such as dermatitis, suggesting its potential role in the development of skin conditions." (PMID 37629111, 2023). "A TRPV3 specific inhibitor that can significantly reverse ear swelling in dermatitis and chronic pruritus." (PMID 36677834, 2023). "The results showed similar attenuation of skin inflammation by either osthole alone or its co-application with flopropione, further confirming the flopropione-mediated alleviation of skin inflammation through inhibition of TRPV3 channels." (PMID 38154600, 2023). "TRPV3 inhibitors from medicinal plants show positive therapeutic effects against pruritus, dermatitis, and skin inflammation in murine models, which establishes them as promising experimental therapeutics for cutaneous diseases." (PMID 37239947, 2023). "In this respect, along with the plant-derived acridone alkaloid inhibitor of TRPV3, the potent inhibition of TRPV3 by an animal-derived Ech A was an intriguing implication for the treatment of skin disorders and pruritis." (PMID 36827119, 2023). "The differences between applying menthol and applying TRPV3’s agonist to skin inflammation remind us of an unclear overlapping effect." (PMID 36439160, 2022). "This suggests that TRPV3 (Gly573Ser) plays a potential role in itching and scratching-related dermatitis." (PMID 36499288, 2022). "Nevertheless, the molecular sites uncovered by the present study would be instrumental in pinpointing the dyclonine-TRPV3 interaction at the molecular level, thereby developing specific therapeutics for chronic pruritus, dermatitis, and skin inflammations." (PMID 33876725, 2021).
dermatitis (continued). "In contrast, excessive upregulation of TRPV3 activity impairs hair growth and increases the incidence of dermatitis and pruritus in both humans and rodents." (PMID 33876725, 2021). "TRPV3 is highly expressed in the epidermal keratinocytes and is involved in skin barrier function, hair growth, and skin inflammation." (PMID 35058747, 2021). "Previous studies also show that aberrant hyperactivity of TRPV3 channels results in spontaneous itch and dermatitis-like symptoms, but the resultant behavior is highly dependent on the background of the animal and the skin microbiome." (PMID 35058747, 2021). "The functional and mechanistic insights obtained on dyclonine-TRPV3 interaction will help to conceive therapeutics for skin inflammation." (PMID 33876725, 2021). "Our previous observations have demonstrated that TRPV3 is upregulated in UVB-induced skin inflammation, while the NF-κB signaling is activated under UV irradiation, leading to the release of various proinflammatory factors and promoting the proliferation of skin keratinocytes and melanocytes." (PMID 40409547, 2025). "In this study, fluoxetine was repurposed for the treatment of skin inflammation and itching.The therapeutic effects of fluoxetine and another drug–repurposed TRPV3 inhibitor flopropione were evaluated at the animal level, and both of them showed promising therapeutic effects." (PMID 40699677, 2025). "Additionally, several synthesized agents, such as a topical anesthetic drug dyclonine and an antispasmodic flopropione, have recently been shown to selectively inhibit TRPV3, reduce itching and alleviate skin inflammation for potential drug repurposing." (PMID 40409547, 2025). "On the basis of previous experiments, we set up dermatitis induced by TRPV3 agonist carvacrol." (PMID 40699677, 2025). "Mechanistic insights and therapeutic potential of fluoxetine in TRPV3-mediated skin inflammation." (PMID 40699677, 2025). "Topical applications of Car for consecutive 4 days in WT mice resulted in ear skin inflammation with significantly increased thickness and ear swelling scores, as compared to Trpv3 KO mice exhibiting a significant reduction of skin thickness and ear swelling scores." (PMID 40409547, 2025). "Our results suggested the antimalarial HCQ may represent a potential alleviator for treating skin inflammation by inhibiting TRPV3 channels." (PMID 39233228, 2024). "Transient receptor potential vanilloid 3 channel (TRPV3) is closely associated with skin inflammation, but there is a lack of effective and specific inhibitors for clinical use." (PMID 39233228, 2024). "Therefore, the physiological role of TRPV3 for thermosensation, hair regulation, and dermatitis has been highlighted." (PMID 38254707, 2024). "Therefore, identifying novel TRPV3 inhibitors holds the potential for developing new strategies to improve skin inflammation and pruritus." (PMID 37629111, 2023). "The antispasmodic agent flopropione inhibits cutaneous overactive TRPV3 channels and may hold repurposing potential for the prevention or therapy of TRPV3-related skin diseases such as dermatitis and chronic pruritus." (PMID 38154600, 2023). "Since TRPV3 is involved in the development of skin inflammation, inhibiting TRPV3 could be a potential treatment strategy." (PMID 37629111, 2023). "All these results demonstrate that inhibition of TRPV3 by flopropione alleviates skin inflammation." (PMID 38154600, 2023). "TRPV3 plays a role in Ca2+ homeostasis due to non-selective ionic conductivity and participates in signaling pathways associated with itch, dermatitis, hair growth, and skin regeneration." (PMID 37239947, 2023). "Although the exact roles of TRPV3 in pain and itch remain to be elucidated, several lines of evidence indicate that TRPV3 is involved at least in the modulation of pain and itch, as well as in the development of dermatitis." (PMID 35890193, 2022).
dermatitis (continued). "As TRPV3 responds to moderate temperatures (30–40°C), dyclonine may thus be used to alleviate skin inflammations persisted in physiological temperatures." (PMID 33876725, 2021). "The clinical scenario targeted by dyclonine treatment echoes the pathological aspects of TRPV3-related skin disorders, suggesting that the therapeutic effects of dyclonine might involve its interaction with TRPV3 sensory channel." (PMID 33876725, 2021). "TRPV3 is widely involved in skin barrier function, hair growth, skin inflammation, pain, and itch." (PMID 30301231, 2018). "Based on the current evidence, TRPV3 may be involved in skin inflammation." (PMID 36439160, 2022). "Interestingly, when Nh mutant is introduced in a different background such as NC/Nga, animals harboring gain-of-function mutation in the Trpv3 gene do not develop any scratching or dermatitis even in the presence of S. aureus." (PMID 35058747, 2021). "Hence, we found that the excessive activity of the TRPV3 channel is not sufficient to cause dermatitis, spontaneous scratching, or any difference in touch-evoked itch." (PMID 35058747, 2021). "Knockout of the Trpv3 gene attenuated UVB-induced mouse dorsal skin erythema, dermatitis score, and thickness, as compared with the wild-type (WT) vehicle group." (PMID 40363831, 2025). "We previously demonstrated that Scu is a selective inhibitor of TRPV3 and Scu alleviates DNFB and carvacrol-induced pruritus and dermatitis through specific suppression of TRPV3." (PMID 39502535, 2024). "Previous studies on mouse models also suggest that TRPV3 mediates the release of pro-inflammatory cytokines, including IL-1α and PGE2, essential mediators of skin inflammation." (PMID 39748945, 2024). "According to our results, this effect could be attributed to the inhibition of TRP channels, especially TRPV3, on skin keratinocytes by alpha-mangostin, the primary xanthone obtained from mangosteen pericarp, as there is a clear relationship between TRPV3 and dermatitis." (PMID 37629111, 2023). "Additionally, our results also confirm that ROSA-mediated inhibition of TRPV3 leads to the downregulation of NF-κB pathway activity, thereby offering further mechanistic insight into the anti-inflammatory activity of ROSA and its analogs in alleviating skin inflammation." (PMID 40409547, 2025).
Pruritus (23 papers, 2016 to 2026). Pruritus is an itch or a sensation that makes a person want to scratch. "Recent studies suggest that mutations leading to enhanced function of TRPV3 are linked to skin inflammation and pruritus." (PMID 41596464, 2026). "Kim found that higher levels of the TRPV3 activator carvacrol were associated with higher NRS scores of the burn scar pruritus index." (PMID 37705977, 2023). "OS is a disease that is caused by the TRPV3 gene mutation, and TRPV3 gene knockout mice have demonstrated significant pruritus inhibitory behavior." (PMID 36677834, 2023). "A recent in vitro and in vivo animal study evaluated the association of TRPV3 with pruritus in inflammatory skin diseases, such as atopic dermatitis and psoriasis." (PMID 36499288, 2022). "A TRPV3 activator, carvacrol, has been reported to cause pruritus in humans." (PMID 37555911, 2023). "For example TRPV3 is implicated in pruritus and its expression in HEK293T cells has provided a successful means for identifying inhibitors, such as the oral anesthetic dyclonine (found in throat sprays and lozenges), and the tropical plant-based acridone citrusinine-II." (PMID 36385768, 2022). "Carvacrol, a natural TRPV3 activator, has been reported to cause pruritus in mice." (PMID 36499288, 2022). "In rodents, gain-of-function mutations of TRPV3 are associated with skin inflammation and pruritus." (PMID 32694980, 2020). "The purpose of this study was to determine whether the TRPV3 activator carvacrol causes pruritus and its topical action on burn scars." (PMID 33113783, 2020). "Inflammation may also play an essential role in the propagation of TRPV3-mediated itchiness, as inflammatory factors such as IL-31 induce high expression of brain natriuretic peptide (BNP), activate TRPV3, upregulate expression of Serpin E1, and cause skin itching." (PMID 39748945, 2024). "Recent research demonstrated that specific diterpenoids from A. paniculata target cutaneous TRPV3 channels, effectively alleviating pruritus." (PMID 40801608, 2025). "DS-Nh mice and WBN/Kob-Ht rats are two kinds of autosomal dominant TRPV3 mutants, both of which appear as pruritus and other symptoms of AD." (PMID 36979447, 2023). "Keratinocyte-expressed TRPV3 is associated with the occurrence of many skin diseases, such as OS, AD, psoriasis, post-burn pruritus, and rosacea, among which OS and AD are the most closely related to TRPV3 and have been studied the most extensively." (PMID 36979447, 2023). "In vivo, intradermal injection of carvacrol induced pruritus in mice that was mediated by TRPV3 and TRPA1." (PMID 37239947, 2023). "Studies on the skin tissues of burn patients showed that the expression of TRPV3 was significantly upregulated in the epidermis of patients with post-burn pruritus." (PMID 36677834, 2023). "In recent decades, many studies have suggested that TRPV3 contributes to detecting pruritus signals." (PMID 36499288, 2022). "Trpvicin, a selective TRPV3 antagonist, has been shown to reduce scratching behavior in mice models of acute and chronic pruritus." (PMID 36613861, 2022). "Inhibition of TRPV3 has been shown to attenuate atopic itch, and patients with atopic dermatitis who experienced pruritus were found to have higher levels of TRPV3 mRNA expression." (PMID 36613861, 2022). "Naturally occurring plant compounds such as coumarin osthole, verbascoside, and citrusinine-II have been shown to selectively inhibit TRPV3 and significantly attenuate pruritus." (PMID 36613861, 2022). "Another study investigated the pruritus and anti-inflammatory effects of a natural verbascoside through temperature-sensitive Ca2+-permeable TRPV3 channels." (PMID 36499288, 2022). "How activation of TRPV3 channels controls the growth of epidermal nerve terminals in control, and chronic itch conditions is a question that remains to be answered." (PMID 35058747, 2021).
Pruritus (continued). "In our previous study, we evaluated the clinical and histopathological characteristics of patients with post-burn pruritus and discovered increased expression of TRPV3, TRPV4 and TRPA1." (PMID 29140280, 2017). "KM-001 is a new experimental medication aimed at alleviating pruritus by inhibiting TRPV3." (PMID 41596464, 2026). "The importance of TRPV3 was already highlighted in postburn pruritus, AD, and allergic pruritus." (PMID 37834183, 2023). "The current research results provide a reference for the function of TRPV3 in PS pruritus." (PMID 37705977, 2023). "The enhanced expression of TRPV3 was also detected in the epidermis of burn scars with pruritus." (PMID 36979447, 2023). "Moreover, TRPV3 plays a dominant role in HDM-mediated itch via a PAR2/TRPV3/TSLP pathway in keratinocytes." (PMID 36385768, 2022). "TRPV3, a non-selective calcium-permeable channel first identified in keratinocytes, was linked to pruritus based on the consequence of gain-of-function mutations in the channel." (PMID 35321329, 2022). "We identified several pruritus-associated genes increased by IDL, IDC and IDL + IDC (e.g., BRCA2, KRT5, TCF4), as well as several such genes decreased by IDL, IDC and/or IDL + IDC (e.g., IL2RG, TRPV3, TNFSF15, IL17RC)." (PMID 36430783, 2022). "The identification of selective TRPV3 activators and inhibitors may potentially lead to beneficial pharmacological interventions for pruritus." (PMID 36499288, 2022). "In the skin, TRPV3 plays a role in both pain and pruritus pathways." (PMID 36613861, 2022). "In chronic itch induced by AEW, various pathways come into action that precipitates to induce hyperinnervation of the epidermis and might require the participation of TRPV3 channels to induce nerve sprouting in the epidermis in chronic itch conditions." (PMID 35058747, 2021). "Given that TRPV3 is mainly expressed in epithelial tissues, it now appears that agents selectively inhibiting TRPV3 may be beneficial in controlling pruritus and may have fewer side effects." (PMID 29140280, 2017). "Moreover, whether the differences in TRPV3 expression profiles in humans and mice indicates different TRPV3 mediated pruritus transmission processes deserves further investigations." (PMID 36979447, 2023). "Thus, systemic application of M/Kv7 opener, RTG, and TA, may indirectly reduce CAR/TRPV3-induced itch by suppressing the excitability of sensory neurons." (PMID 32694980, 2020). "Within this integrated microenvironment, specific TRP channels, notably TRPA1, TRPV1, TRPV3, and TRPV4, exhibit a remarkable ability to simultaneously influence both fibrotic and pruritus-related signaling pathways." (PMID 41596464, 2026). "In addition, TRPV3-mediated PS pruritus may be related to the expression of PAR2 and TSLP." (PMID 37705977, 2023). "Therefore, the expression of TRPV3 in PS may be positively correlated with the degree of pruritus, and the upregulation of TRPV3 channels may be related to the increased expression of PAR2 and TSLP and the involvement of the PAR2-TSLP positive feedback pathway." (PMID 37705977, 2023). "In this review, we discuss the role of TRP channels TRPA1, TRPV1, TRPV2, TRPV3, TRPV4, TRPM8, and TRPC3/4 in acute and chronic pruritus." (PMID 38139833, 2023). "It was shown that certain thermosensitive TRP channels, especially TRP vanilloid 1 (TRPV1), TRPV3, TRPV4 and TRP ankyrin 1 (TRPA1), have important roles in the pathogenesis of pruritus as well as pain." (PMID 29140280, 2017). "We found that TRPV3 and TSLP were increased in burn-scar tissues, especially in burn scars with pruritus." (PMID 29140280, 2017). "There have been reports that TRP channels other than TRPV3, such as TRPV1/4, TRPA1, and TRPM6/7 contribute to pruritus." (PMID 29140280, 2017). "In addition, compared with normal tissues, the expression of TRPV3 and TSLP in KCs in burn scars was upregulated, especially in burn scar tissues with pruritus." (PMID 37705977, 2023).
Pruritus (continued). "Further research is expected to determine whether the combination of TRPV3 with TSLP and PAR2 inhibitors can provide a feasible solution for PS pruritus." (PMID 37705977, 2023). "TRPV3 mRNA expression is higher in AD patients with pruritus than AD patients without pruritus and healthy controls." (PMID 37555911, 2023). "Conclusively, TRPV3 may contribute to pruritus in burn scars through TSLP, and can be considered a potential therapeutic target for post-burn pruritus." (PMID 29140280, 2017). "To evaluate the role of the TRPV3 channel on PAR2 function, we compared the intracellular Ca2+ level with Fluo-3, with PAR2 agonist in TRPV3 pretreated keratinocytes cultured from normal tissue or burn-scarred tissue (with or without pruritus)." (PMID 29140280, 2017). "PS pruritus may be related to the expression of PAR2 and TSLP, which is mediated by TRPV3 channels." (PMID 37705977, 2023). "Therefore, upregulation of the TRPV3 channel in the scar tissue with pruritus may lead to an increase in TSLP expression, which may be one of the mechanisms of post-burn pruritus." (PMID 29140280, 2017). "Like TRPV3, TRPV4 mRNA expression was increased in burn patients with pruritus compared to burn patients without pruritus and normal skin, and is positively correlated with the intensity of pruritus." (PMID 37555911, 2023). "In this study we demonstrated the relationships of PAR2, TRPV3 and TSLP in keratinocytes from scars with or without pruritus." (PMID 29140280, 2017).